TCP1 (t-complex 1)
Diseases named in the same sentence as TCP1 in open-access papers (continued):
Sharing a sentence is not in itself a finding about the gene and the disease.
leukemia (2 papers, 2021 to 2025). A malignant (clonal) hematologic disorder, involving hematopoietic stem cells and characterized by the presence of primitive or atypical myeloid or lymphoid cells in the bone marrow and the blood. "TCP1 showed higher expression in the adriamycin-resistant leukemia cell line HL60/A and K562/A, comparing to their respective parent cells HL60 and K562 cells." (PMID 34750375, 2021). "To investigate the potential clinical significance of TCP1 in leukemia, we examined the relative expression of TCP1 mRNA in PB mononuclear cells from 66 newly diagnosed leukemia patients and 41 healthy donors." (PMID 34750375, 2021). "Likewise, there was also a higher level of TCP1 in various leukemia cells compared to the normal bone marrow." (PMID 40430849, 2025). "To further elucidate the potential mechanism of TCP1-mediated AML cell survival, we analyzed its regulatory effects on PLK1 (a cell cycle regulator) and AML1-ETO (a leukemia-associated fusion protein) using AML cell lines with constitutive TCP1 knockdown (HL-60-G4-shTCP1 and Kasumi-1-shTCP1)." (PMID 40430849, 2025). "The data indicated that TCP1 might be involved in the leukemia development." (PMID 34750375, 2021).
liver cancer (2 papers, 2015 to 2024). An epithelial or non-epithelial malignant neoplasm that arises from the liver.
Pancreatic Cancer (2 papers, 2017 to 2023). "In conclusion, WDR37 may inhibit the progression of pancreatic cancer and promote tumor immune response by promoting the degradation of TCP1 protein in pancreatic cancer." (PMID 38304253, 2023).
AIDS (1 paper, 2021). A syndrome resulting from the acquired deficiency of cellular immunity caused by the human immunodeficiency virus (HIV). "Lastly, TCP1 chaperon complex member 8 (CCT8) was found to be an important marker for disease progression towards AIDS, showing low expression during slow/non- progression, and increasing correspondingly in AIDS." (PMID 34835333, 2021).
ankylosing spondylitis (1 paper, 2023). An autoimmune chronic inflammatory disorder characterized by inflammation in the vertebral joints of the spine and sacroiliac joints. "TCP1 is also involved in bone pathology, and specifically, Ankylosing Spondylitis (AS)-induced heterotopic ossification." (PMID 36983761, 2023).
autoimmune disease (1 paper, 2024). A disorder resulting from loss of function or tissue destruction of an organ or multiple organs, arising from humoral or cellular immune responses of the individual to their own tissue constituents. "The reason anti-TCP1 antibodies were detected in some BD and SSc patients appears to be that autoimmune diseases, including SLE, produce a variety of autoantibodies." (PMID 39201300, 2024). "This suggests that the anti-TCP1 antibody could be a reliable biomarker for distinguishing SLE from other autoimmune diseases and NCs." (PMID 39201300, 2024). "The results confirmed the detection of anti-TCP1 antibodies in 79 of 100 patients with SLE, with substantially elevated expression compared to both NCs and patients with other autoimmune diseases." (PMID 39201300, 2024).
Bardet-Biedl syndrome (1 paper, 2026). A ciliopathy with multisystem involvement. "The ADGRV1 intracellular bait pulled down proteins involved in actin-based cell projections, the chaperone-containing TCP-1 complex, and the Bardet-Biedl syndrome complex." (PMID 41654259, 2026).
benign ovarian tumors (1 paper, 2021). "TCP1 protein expression in OC or borderline tissues was significantly higher than that in benign ovarian tumors and normal ovarian tissue." (PMID 34162426, 2021).
breast tumor (1 paper, 2019). "For instance, the homolog of one of our identified top-hits, CCT2, along with TCP1, has recently been linked as a driver mutation in breast tumor formation." (PMID 31270132, 2019).
colonic adenocarcinoma (1 paper, 2016). "The cytostatic activities of IFNγ and TCP-1/IFNγ were determined in a murine fibrosarcoma cell line (L929) and a mouse colonic adenocarcinoma cell line (Colon 26)." (PMID 27342639, 2016).
Down syndrome (1 paper, 2014). "It is notable that TCP1 levels are abnormal in foetal Down’s syndrome." (PMID 25080104, 2014).
ependymal tumor (1 paper, 2014). A group of neoplasms which arise from the ependymal lining of the cerebral ventricles and from the remnants of the central canal of the spinal cord. "Some genes mapping to the long arm of chromosome 6 have previously been reported to be downregulated in ependymal tumors, including SASH1 [a candidate tumor suppressor gene in breast and colon cancer], TCP1 (involved in tubulin function), ADM1 and CDK11 (involved in cell proliferation)." (PMID 24939246, 2014).
iron deficiency (1 paper, 2012). "For example, actin-related protein 3 and tubulin α-1 chain were key gatekeeper proteins associated with cytoskeletal functions, whereas ADP-ribosylation factor-like 3, dihydropyrimidinase-related protein 2 and chaperonin containing TCP1 were identified in this role with iron deficiency." (PMID 23110188, 2012).
lupus (1 paper, 2024). "Next, we hypothesized that the anti-TCP1 antibody could be a better biomarker than the anti-RPLP0, RPLP1, and RPLP2 antibodies, which were already known lupus autoantibodies." (PMID 39201300, 2024).
lymphoid neoplasm (1 paper, 2015). A neoplasm composed of a lymphocytic cell population which is usually malignant (clonal) by molecular genetic and/or immunophenotypic analysis. "Based on these results, we concluded that TCP-1 played a crucial role in the inhibition of lymphoid neoplasm metastasis." (PMID 26556873, 2015). "It indicates that TCP-1 may be a crucial downstream molecular of P2X7R and plays a novel role in lymphoid neoplasm metastasis." (PMID 26556873, 2015).
lymphoma (1 paper, 2015). A malignant (clonal) proliferation of B- lymphocytes or T- lymphocytes which involves the lymph nodes, bone marrow and/or extranodal sites. "In this study, we have proved that silence P2X7R expression can significantly decreased the expression of TCP-1 both in vivo and in vitro, the correlative expression of P2X7R and TCP-1 was also founded in human lymphoma tissues." (PMID 26556873, 2015). "The positive correlation between P2X7R and TCP-1 was also proved in both lymphoma and benign lymphadenopathy tissues from patients." (PMID 26556873, 2015). "In addition, we found that down-regulating TCP-1 can greatly attenuate the metastatic capability of the mouse lymphoma cells." (PMID 26556873, 2015). "We have verified that TCP-1 shRNA a could silence the expression of TCP-1, and then we want to know whether the reduced expression of TCP-1 could regulate lymphoma progression and metastasis." (PMID 26556873, 2015). "P2X7R and TCP-1 were observed expressing in both lymphoma and benign lymphadenopathy." (PMID 26556873, 2015). "We propose that TCP-1 may be a new target for the therapy of lymphoma." (PMID 26556873, 2015). "In order to know the relationship between P2X7R and TCP-1 in human lymphoma, immunohistochemical analysis about P2X7R and TCP-1 was performed." (PMID 26556873, 2015). "We detected the expression of TCP-1 in three kinds of murine lymphoma cell lines, P388D1, L5178Y and L1210, RT-PCR and Western blot confirmed that TCP-1 was indeed expressed in these cell lines." (PMID 26556873, 2015). "In lymphoma cases, the cases expressed P2X7R and TCP-1 (P2X7R+/TCP-1+) was more than 86%." (PMID 26556873, 2015).
mastocytosis (1 paper, 2024). A clonal myeloproliferative neoplasm characterized by the proliferation and accumulation of neoplastic mast cells in one or multiple organs or organ systems. "We also found TCP1 to be predicted in mastocytosis and B-cell precursor-ALL, whose high expression has been associated with AML drug resistance and poor survival through the activation of AKT/mTOR signaling." (PMID 38769532, 2024).
parasite (1 paper, 2016). "Moreover, the importance of protein turnover/folding/modifications during parasite infections is underscored by differential modulations of the UDE homolog, TcP-1 components and various molecular chaperones identified in the current study." (PMID 27485005, 2016).
primary biliary cholangitis (1 paper, 2020). Primary biliary cholangitis (PBC) is a chronic and slowly progressive cholestatic liver disease of autoimmune etiology characterized by injury of the intrahepatic bile ducts that may eventually lead to liver failure. "Our results suggest that hsa-miR-23b is involved in pathophysiology of primary biliary cholangitis through interleukin-12 signaling via regulation of CNN2, JAK1, LMNB1, MTAP, SOD2, and TCP1." (PMID 33036164, 2020).
thyroid cancer (1 paper, 2016). "Aim of this study was to test the effect of IFNγ on the basal and TNFα-stimulated secretion of CXCL8 in TCP-1 and BCPAP thyroid cancer cell lines (harboring RET/PTC rearrangement and BRAF V600e mutation, resp)." (PMID 27555670, 2016).
tumor (30 papers, 2014 to 2025). "Further, it has been reported that TCP-1 interacts with some tumor metastasis-associated proteins, such as tubulins and actins." (PMID 26556873, 2015). "Abnormal expression of TCP1 has been associated with tumor cell proliferation and drug resistance." (PMID 40544380, 2025). "High TCP1 expression is associated with poor prognosis in various tumours." (PMID 39174525, 2024). "The ability of TCP-1-modified TNVs to actively target and aggregate at tumor locations was demonstrated by in vivo imaging of small animals." (PMID 40520210, 2025). "In the mouse AML model, it was found that the expression of TCP1 increased with the increasing tumor generation." (PMID 40430849, 2025). "Functional consequences of TCP1 silence were evaluated through in vitro proliferation assays and in vivo tumor growth monitoring." (PMID 40430849, 2025). "While heat shock proteins (HSPs) have long been implicated in the molecular mechanisms of tumor phenotype progression, recent attention has turned to CCT (chaperonin containing TCP1), orchestrating proteostasis." (PMID 41516249, 2025). "To further validate the differential expression of TCP1, we examined the TCP1 in tumor tissues from different generations of HL-60 cells by IHC staining." (PMID 40430849, 2025). "FTY720 disrupted TCP1′s chaperone function, leading to cell cycle arrest, apoptosis, and reduced xenograft tumor growth in murine models." (PMID 40430849, 2025). "While HSPs have long been implicated in the molecular mechanisms of tumor phenotype progression, recent attention has turned to CCT (chaperonin containing TCP1), also known as TRiC (TCP-1 Ring Complex)." (PMID 41516249, 2025). "TCP1 promotes tumor migration via the Wnt7b/β‐catenin signaling pathway, enhancing cell proliferation." (PMID 41312091, 2025). "By measuring TCP1 expression levels in tumour tissues, we found higher TCP expression levels in patients with DLBCL than in lymph node tissues with reactive hyperplasia, which was associated with significantly shorter OS." (PMID 39174525, 2024). "In conclusion, our results suggest that in DLBCL, high TCP1 expression enhances the sensitivity of GCB tumour cells to ferroptosis and serves as a marker of poor prognosis in patients with non-GCB DLBCL." (PMID 39174525, 2024). "Western blotting showed that the phosphatidylinositol-3 kinase (PI3K) signaling pathway was activated in the tumor invasion in EOC driven by TCP1." (PMID 34162426, 2021). "Immunofluorescence staining of tumor tissues demonstrated that TCP1 overexpression inhibited the LC3 expression." (PMID 34750375, 2021). "We aimed to identify the association between the expression of TCP1 and the development of epithelial OC (EOC) and patient prognosis, and explore the underlying mechanisms of TCP1 on the tumor progression of OC cells." (PMID 34162426, 2021). "Most interestingly, combination treatment by TCP-1/TNFα and TCP-1/IFNγ dramatically inhibited tumor growth." (PMID 27342639, 2016). "The TCP-1/TNFα and TCP-1/IFNγ combined treatment group inhibited tumor growth by different mechanisms from targeted TNFα or IFNγ alone which is highly associated with antitumor immunity." (PMID 27342639, 2016). "Compared with the control group, TNFα or IFNγ slightly but not significantly suppressed tumor growth, while TCP-1/TNFα or TCP-1/IFNγ significantly decreased tumor size compared with their unconjugated counterparts." (PMID 27342639, 2016). "After 24 h treatment, TCP-1/IFNγ induced more MHC-I expression inside the tumor than control or IFNγ, indicating more IFNγ was accumulated in the tumor by targeted delivery by TCP-1 peptide." (PMID 27342639, 2016). "Targeted delivery of TNFα or IFNγ by TCP-1 peptide exhibited better antitumor activity than unconjugated format by inducing more tumor apoptosis and also enhancing antitumor immunity shown by increased infiltration of T lymphocytes inside the tumor." (PMID 27342639, 2016).
tumor (continued). "We used the dose of 1 μg/mouse for TNFα and TCP-1/TNFα and 5 μg/mouse for IFNγ and TCP-1/IFNγ according to previous experiment which indicated that 5 μg TCP-1/IFNγ can induce maximal anti-tumor effect." (PMID 27342639, 2016). "To further clarify how the cells in the tumor died after TCP-1/TNFα and TCP-1/IFNγ combined treatment, we used the colon 26 cells to determine the effect of TNFα combined with IFNγ in vitro." (PMID 27342639, 2016). "We found that TNFα (1 μg/mouse) or IFNγ (5 μg/mouse) slightly increased tumor apoptosis while conjugation with TCP-1 peptide significantly inhibited tumor growth and increased tumor cell apoptosis." (PMID 27342639, 2016). "TCP-1/TNFα combined with TCP-1/IFNγ induced massive cell death in the tumor (>90 %) as shown by the TUNEL staining and also cell death of the tumor vasculature." (PMID 27342639, 2016). "More importantly, combination therapy of TCP-1/TNFα and TCP-1/IFNγ synergistically suppressed tumor growth and alleviated systematic toxicity associated with untargeted therapy." (PMID 27342639, 2016). "The data demonstrated that targeted delivery of TNFα combined with IFNγ by TCP-1 peptide drastically inhibited tumor growth than single treatment and at the same time alleviated systematic toxicity induced by non-targeted TNFα and IFNγ." (PMID 27342639, 2016). "Concordantly, both TUNEL staining and immunofluorescence staining for cleaved caspase-3 revealed that TNFα or IFNγ increased the number of apoptotic cells inside the tumor while conjugation with TCP-1 further induced apoptosis." (PMID 27342639, 2016). "We found that the expression of TCP-1 in tumor metastatic lymph nodes was also decreased while P2X7R was silenced." (PMID 26556873, 2015). "A decreased level of TCP-1 lowers the content of cyclin E, which reduces the capability of tumor cell division and proliferation and, thus, reduces tumor metastasis." (PMID 26556873, 2015). "A decreased level of TCP-1 reduces actin and tubulin synthesis, thus reducing the amount of cell motility-related proteins and weakening tumor metastatic potential." (PMID 26556873, 2015). "After that we analyzed the results of two groups by mass spectrum, TCP-1 appeared to have a close relationship with P2X7R in tumor metastasis." (PMID 26556873, 2015). "TCP-1 can interact with a variety of proteins, including cytoskeletal proteins that impact on tumor metastasis." (PMID 26556873, 2015). "Furthermore, we used Tet-on technology to construct HL-60-G4-tet-shTCP1 cells that can knock down TCP1 by adding doxycycline (Dox+) and used this cell line to construct a xenograft tumor model in nude mice." (PMID 40430849, 2025). "Compared to the control group (Dox−), Dox+ significantly induced TCP1 knockdown in tumor tissues and reduced tumor volume, which further verified that targeting TCP1 could be a potential treatment option for AML." (PMID 40430849, 2025). "TCP1 can promote tumour cell proliferation via PI3K/AKT/mTOR pathway activation." (PMID 39174525, 2024). "In summary, WDR37 may play an anti-tumor role by mediating the degradation of TCP1 complex through K48 ubiquitin modification." (PMID 38304253, 2023). "The results of functional analysis and in vitro experiments indicated that WDR37 may promote the degradation of TCP1 complex to inhibit tumor and improve immune cell infiltration." (PMID 38304253, 2023). "Chaperonin-containing TCP-1 promotes tumor progression, chemoresistence and metastasis." (PMID 35806366, 2022). "Our previous study has demonstrated that low dose TCP-1/TNFα could normalize tumor blood vessel, enhance the intratumoral accumulation of anticancer drug 5-FU, thus potentiating its antitumor activity." (PMID 27342639, 2016). "To directly test whether TCP-1 peptide could deliver IFNγ to tumor vasculature, we injected 50 nmol IFNγ or TCP-1/IFNγ into mice bearing orthotopic CRC through tail veins." (PMID 27342639, 2016).